RHEBP1 (RHEB pseudogene 1)
Synonyms: RHEB; formerly RHEB1
Gene: Transcribed processed pseudogene on chromosome 10 (46,634,911 to 46,635,466, reverse strand). Ensembl gene ENSG00000229927.
Diseases named in the same sentence as RHEBP1 in open-access papers:
RHEBP1 is named in the same sentence as 28 diseases in open-access papers, as found by Europe PMC text mining. Sharing a sentence is not in itself a finding about the gene and the disease.
RHEBP1 shares sentences with these, for which no sentence is quoted: tumor (5 papers); acute myeloid leukemia (4); cancer (2); colorectal cancer (2); tuberous sclerosis (2); acute kidney injury (1); allergic asthma (1); Arrhythmia (1); asthma (1); autism (1); breast carcinoma (1); chronic kidney disease (1); colon cancer (1); diabetes (1); epilepsy (1); heart failure (1); hypertrophic cardiomyopathy (1); Hypoglycemia (1); Intellectual disability (1); kidney (1); leukemia (1); Lissencephaly (1); lung carcinoma (1); Myocardial fibrosis (1); myocardial hypertrophy (1); myocardial infarction (1); pancreatic cancers (1); Seizure (1).